CFAP300 (cilia and flagella associated protein 300)
Description:
Cilium- and flagellum-specific protein that plays a role in axonemal structure organization and motility. May play a role in outer and inner dynein arm assembly.
Synonyms: C11orf70; MGC13040; FBB5; DNAAF17; CILD38
Tractability: No criterion of Open Targets' tractability assessment is met for any kind of drug.
Gene: Protein-coding gene on chromosome 11 (102,047,435 to 102,084,554, forward strand). Ensembl gene ENSG00000137691.
Subcellular location: Cytoplasm; Cytoplasm, cytoskeleton, cilium axoneme
Subcellular location (Human Protein Atlas): Centrosome; Primary cilium
Gene Ontology:
Molecular function: protein binding
Cellular component: cytoplasm; motile cilium; axoneme
Genetic constraint (gnomAD): Loss-of-function variants: 20 observed, 20.96 expected, observed/expected ratio (o/e) 0.95, 90% interval 0.67 to 1.39. The upper end of that interval is the gene's LOEUF score, 1.39, which puts it in group 5 of 6, group 1 being the genes least tolerant of losing a copy. Missense variants: 252 observed, 236.06 expected, observed/expected ratio (o/e) 1.07, 90% interval 0.96 to 1.18. Synonymous variants: 77 observed, 82.2 expected, observed/expected ratio (o/e) 0.94, 90% interval 0.78 to 1.13.
Gene-disease validity (ClinGen):
ClinGen rates the evidence that CFAP300 causes each of these diseases.
ciliary dyskinesia, primary, 38 (autosomal recessive): Definitive.
Homologues: Orthologues: chimpanzee CFAP300 (99% identical), pig CFAP300 (92% identical), guinea pig CFAP300 (85% identical), dog CFAP300 (85% identical), mouse Cfap300 (84% identical), rat Cfap300 (80% identical), macaque CFAP300 (76% identical), rabbit CFAP300 (73% identical), tropical clawed frog cfap300 (59% identical), zebrafish cfap300 (50% identical).
Diseases named in the same sentence as CFAP300 in open-access papers:
CFAP300 is named in the same sentence as 3 diseases in open-access papers, as found by Europe PMC text mining. Sharing a sentence is not in itself a finding about the gene and the disease. The quoted sentences say what the papers report.
primary ciliary dyskinesia (2 papers, 2023 to 2025). A rare, genetically heterogeneous, primarily respiratory disorder characterized by chronic upper and lower respiratory tract disease. "For example, mutations in CFAP300 have been associated with Primary Ciliary Dyskinesia (PCD)." (PMID 36595063, 2023).
male infertility (1 paper, 2020). The inability of the male to effect fertilization of an ovum after a specified period of unprotected intercourse. "Male infertility has also been detected in PCD patients with mutations in axonemal dynein assembly factors LRRC6 (leucine-rich repeat containing 6), ZMYND10 (zinc finger MYND-type containing 10) and cilia and flagella-associated protein 300 (CFAP300)." (PMID 31781811, 2020).
CFAP300 also shares sentences with these, for which no sentence is quoted: Hydrocephalus (1 paper).